ATR (ATR checkpoint kinase)
Diseases named in the same sentence as ATR in open-access papers (continued):
Sharing a sentence is not in itself a finding about the gene and the disease.
cancer (continued). "Additionally, the use of ATR (ataxia telangiectasia and Rad3-related protein) inhibitors alongside PARP inhibitors has been shown to further intensify replication stress and drive tumor cell apoptosis in certain cancer models." (PMID 40895460, 2025). "In the next section we describe the main ATR, ATM, Chk1 and Chk2 inhibitors used in preclinical experiments and/or clinical trials and explain how these drugs, alone or in combination, may help in cancer treatment." (PMID 40422251, 2025). "Hence, reducing MYC activity limits the cell’s ability to cope with replication stress, and when this is coupled with inhibition of key DNA repair pathways such as ATR/CHK1, WEE1, DNA-PKcs, or PARP, cancer cells can be pushed toward irreversible genomic instability." (PMID 41561634, 2025). "Unlike ATR, which is essential in numerous organisms and whose mutations can lead to embryonic lethality, ATM is not essential for viability and is often mutated, contributing to cancer development." (PMID 39968096, 2025). "In conclusion, the synthetic lethality between ATR/CHK1 and POLA1 might represent a novel and promising approach for individualized cancer therapy: First, alterations of POLA1 could serve as a screening parameter for increased sensitivity towards ATR and CHK1 inhibitors." (PMID 39128273, 2024). "The Pommier group has demonstrated that SLFN11 could inhibit stressed replication forks independent of ATR and this blockage-induced cancer cell death by SLFN11 was deemed irreversible." (PMID 38791884, 2024). "Therefore, the development of approaches directed to the inhibition of ATR and CHEK1 in malignant neoplasms, particularly in ECE, could increase the effectiveness of therapeutic measures to prevent recurrence/metastases from occurring." (PMID 38669256, 2024). "Therefore, while ATR inhibitors show great promise in cancer therapeutics, it is critical to assess why these adverse effects occur in the light of emerging non-canonical roles of ATR." (PMID 39456630, 2024). "Furthermore, the inhibition of the ATR effector kinase CHK1 has been observed to abrogate the G2/M checkpoint after irradiation, resulting in the production of micronuclei and the activation of the type I IFN pathway in cancer cells." (PMID 38474014, 2024). "We recently reported that recombinant hAPE1 protein can form biomolecular condensates in vitro in an DNA/RNA-independent manner, and that ectopically overexpressed YFP-hAPE1 can be recruited to the nucleoli of human cancer cells in the absence of DNA damage to promote the ATR signaling." (PMID 39112456, 2024). "Ataxia telangiectasia mutated Protein (ATM) and ataxia telangiectasia and Rad3-related (ATR) are members of the phosphatidylinositol 3-kinase (PI3K)-related kinase (PIKK) protein family, and are frequently activated as checkpoint sensors during cancer treatment therapy." (PMID 37144123, 2023). "Our data provide strong evidence that combining ATR and TOP1 inhibitors in cancer cells triggers robust immune response signaling and secretion of pro‐inflammatory factors, and thus might transform “cold” tumors into “hot” tumors, which are more likely to respond to systemic immunotherapy." (PMID 35957613, 2023).
cancer (continued). "In various cancer models, Wee1 inhibition promotes accumulation of cytosolic dsDNA, leading to activation of the cGAS-STING pathway, increased type I interferon target gene expression when delivered alone, as well as in combination with ATR inhibitors or immune checkpoint blockade." (PMID 36106115, 2022). "Therefore, in this study, the translational downregulation of ATR, a couple with the induction of cellular DNA damage might contribute to selectively targeting MCF-7 cells as well as potentially other cancer cells by THMGT in future investigations." (PMID 35287310, 2022). "In this review, we will discuss ATR inhibitors, Polθ inhibitors and WRN inhibition as potential treatments for cancer and highlight how lessons from the discovery and development of PARPi and the study of PARPi resistance could inform the clinical development and use of new DDR inhibitors." (PMID 35567571, 2022). "Targeting DNA damage checkpoint kinase, such as ATR/ATM, could be promising for cancer treatment." (PMID 35287310, 2022). "For example, ATR is synthetic lethal with the closely related PIKK family kinase ATM, suggesting ATRi could serve some utility in the treatment of cancers, such as gastric cancer, where ATM is defective." (PMID 35567571, 2022). "Cancer cells were treated with ATR inhibitors, with or without a MEK inhibitor or temozolomide." (PMID 35740680, 2022). "Importantly, since a direct connection between R-loops and cancer has been recognised, WRNIP1 could be employed as a target to further sensitise cancer cells to inhibitors of ATR or CHK1 that are currently under clinical evaluation." (PMID 35163467, 2022). "Indeed, the presence of DSBs (likely to be higher in HRD tumors) has been found to upregulate PD-L1 expression in cancer cells, in a process that requires ATM/ATR/Chk1 kinases and is driven by STAT1 and STAT3 signaling, providing a potential explanation for the elevated PD-L1 seen in HRD tumors." (PMID 36362142, 2022). "Thus, dysfunctionalities of other DDR factors involved in HR-mediated DSB repair, such as RAD51, ATR, ATM, and CHK1/2, are being studied to expand the spectrum of cancer patients that could benefit from PARP inhibitor treatments." (PMID 34363951, 2021). "Therefore, disrupting PARP, ATM, ATR/CHK1, WEE1, or DNA-PK activity may selectively contribute to accumulation of DNA damage in tumors, sensitize cancer cells to killing, and ultimately induce cell death." (PMID 34930377, 2021). "Thus, using targeted agents for DDR pathways, including inhibitors of ATR/CHK1, PARP, ATM, cyclin-dependent kinase 4/6 (CDK4/6), DNA-PK, WEE1, and aurora kinase B (AURKB) opens new exciting avenues for clinical development of ICB for cancer treatment." (PMID 34930377, 2021). "Notably, HMGA2 is also involved in the modulation of DNA damage response by altering the expression or phosphorylation of DNA damage checkpoint proteins including ATM and ATR/CHK1 axis, leading to the increased sensitivity to diverse genotoxic insults upon HMGA2 downmodulation in cancer cells." (PMID 34887387, 2021). "However, the impact of TopBP1 overexpression on ATR/Chk1 activation and cancer development has not been investigated." (PMID 33556369, 2021). "Moreover, DADS resisted the activation of the G2/M gene damage checkpoints by relying on Mec1 (ATR) and Tel1 (ATM) to inhibit DNA repair, which could improve the efficacy of DNA damage-based cancer therapies." (PMID 34745287, 2021). "Similarly, ATR expression in cancer cells was an independent prognostic factor for OS, but not for DFS." (PMID 32414408, 2020). "Additionally, three unsolicited variants in ATR, BLM (in two individuals), and FANCB genes presented potential cancer susceptibility, were not reported to patients." (PMID 31937788, 2020).
cancer (continued). "Given the critical importance of FANCI as an ATR target, the phosphorylation state of the FANCI-3SQ cluster may be an appropriate biomarker of the effectiveness of several classes of ATR kinase inhibitor currently in clinical trial for the treatment of cancer." (PMID 32117957, 2020). "Although APE2 plays essential roles in base excision repair and ATR-Chk1 DNA damage response (DDR) pathways, it remains unknown how the APE2 gene is altered in the human genome and whether APE2 is differentially expressed in cancer patients." (PMID 32111912, 2020). "It has recently been reported that the ATR/Chk1 pathway plays a key role in promoting RRM2 accumulation by stabilizing E2F1 in the S-phase cells, which may be important for countering the replication stress in cancer cells." (PMID 31324785, 2019). "Moreover, our data suggest that inhibitors of ATR and CHK1 may have different effects in cancer therapy." (PMID 30674555, 2019). "This distinction is important to note in regard to therapeutic treatment of cancers with ATR inhibitors, which in this case may not improve outcomes." (PMID 32039009, 2019). "Thus, ATR and Chk1 appear to be even more important in tumor than normal cells, in which it is critical for cancer cells for survival, in coping replication stress and in preventing cell death." (PMID 29870526, 2018). "Furthermore, in U2OS cells with impaired G1 checkpoint control for various reasons relevant to cancer (e.g., overexpression of cyclin D1, cyclin E, CDK2, MDM2 or human papilloma virus E2), expression of ATR-KD or treatment with caffeine augmented the sensitisation of cells to DNA damage." (PMID 28448462, 2017). "Similarly, others have also noted that ATR-Chk1 pathway inhibitors sensitize cancer cells to cisplatin independent of ATR kinase activity." (PMID 26657501, 2016). "Therefore, based on our findings, a combinatorial regimen targeting ATR and PARP1 pathways during NTP treatment might have the potential for development as an enhanced cancer therapy with favorable therapeutic responses." (PMID 27145275, 2016). "Thus, the addition of ATR-inhibitor to standards of care treatments, including ICB, was shown to enhance the antitumor T-cell response, rising a very specific effect of ATR-inhibitor on the immune compartment on top of its inhibitory impact on the cancer cell DNA-repair machinery." (PMID 40139833, 2025). "Moreover, inhibitors targeting different stages of the cell cycle, such as ATM inhibitors, ATR inhibitors, WEE1 inhibitors, and CHK1 inhibitors, have been developed in recent years, and their combination with PARP inhibitors has demonstrated enhanced anti-cancer efficacy." (PMID 40606759, 2025). "However, targeting ATR might be a selective strategy for cancer cells but not normal cells, making ATR an attractive target compared to chemotherapy administration." (PMID 38539474, 2024). "Notably, APE1 forms biomolecular condensates in vitro and in nucleoli independent of its nuclease activity to promote the ATR-Chk1 DDR pathway activation in cancer cells, and APE1 is proposed as a new direct activator of the ATR kinase, in addition to TopBP1 and ETAA1." (PMID 37216274, 2023).
cancer (continued). "Moreover, our study further identified that ATR inhibitor AZD6738 can be used as a combinational drug with oxaliplatin to overcome the chemoresistance to oxaliplatin induced by PAK6 in vitro and in vivo, providing a potential possibility for future consideration in clinical cancer treatment." (PMID 35902562, 2022). "Thus, many cancer cells may not have full functionality of ATR response owing to overexpression of TopBP1." (PMID 33556369, 2021). "Importantly, ATR’s fundamental roles in the RSR, including limiting origin firing and promoting nucleotide synthesis, act to prevent RPA exhaustion and replication catastrophe, and likely present a key survival mechanism for cancer cells with high endogenous replication stress." (PMID 34329458, 2021). "To date, the complete spectrum of the interplay between ATM, DNA-PKcs and ATR, has not been fully uncovered, but could provide a better understanding of the synthetic lethality and of the synergistic effects of ATMi, DNA-PKcsi and ATRi in cancer therapy." (PMID 32015826, 2020). "In addition to the potential of ATR and CHK1 inhibitors as chemo- and radiosensitisers, data suggests that they may also have single agent activity through exploitation of certain phenotypic alterations in cancer." (PMID 28448462, 2017). "The decrease in mTORC1 activity upon ATR inhibition, but not ATM inhibition, in another cancer cell line (HeLa) was also rescued by supplementation with cholesterol (Fig. EV4A,B)." (PMID 40514450, 2025). "We found that the combined treatment with radiation and ATR inhibitors can increase the release of HMGB1 and secretion of ATP, but not surface-presentation of CALR, in several human cancer cell lines." (PMID 37346039, 2023). "CDC25A is overexpressed in cancer and promotes tumorigenesis; interestingly, a genome-wide CRISPR screen showed that the absence of CDC25A leads to ATR inhibitor resistance." (PMID 36499000, 2022). "Conversely, the exposure of ALT-positive cancer cells to TXT compounds failed to evoke the activation of both ATM- and ATR-dependent signaling cascade." (PMID 36437244, 2022). "Because of their non-redundant and coupled functions, ATR and ATM kinases were for a long time seen as putative co-targets for drug combination in cancer therapy." (PMID 35361811, 2022). "In particular, components of ATR and FA pathways are increased HPV positive OPSCCC cells that also contain enhanced levels of APOBEC3B as compared to HPV negative cancers and normal cells." (PMID 34578402, 2021). "Cancer cell lethality was significantly enhanced when ATM was inhibited in combination with DUTi and epirubicin, but not with ATR inhibition." (PMID 33824328, 2021). "Here we demonstrate that the degree of ATR/Chk1 activation is regulated by TopBP1 in a biphasic, concentration-dependent manner in a nontransformed MCF10A cell line and several cancer cell lines, including H1299, MDA-MB468, and U2OS." (PMID 33556369, 2021). "Moreover, DNA damage proteins and cancer cells have specific properties, including cancer-specific DDR defects and lack of G1 checkpoint control, that may highlight particular vulnerabilities of the cancer, supporting PARP, ATR, ATM, CHK1/2, and WEE1 as therapeutic targets." (PMID 34930377, 2021). "However, the applicationof SL modulators still has a long way to go, as not all cancer subtypeshave clearly defined deficiency, such as has been seen with the applicationof PARP1 and BRCA1/2 inhibitors or the 29 clinical trials currentlyinvolving ATR inhibitors." (PMID 33135887, 2020).
cancer (continued). "We found that unlike the checkpoint sensors ATR, RAD9, and RAD17, the downstream components of the ATR pathway Claspin, Timeless, and CHK1 show a correlated overexpression in cancer cells." (PMID 30796221, 2019). "In contrast, the expression of the checkpoint sensors ATR, RAD9, and RAD17 was only modestly increased in cancer samples relative to normal tissues, and did not correlate with the downstream components of the pathway." (PMID 30796221, 2019). "Therefore, over-expression of Claspin (and other FPC components) in cancer cells may constitute a reservoir of these proteins that allows the fast reassembly of functional FPCs that will promote fork restart and RS tolerance by a mechanism independent of the ATR-Chk1 checkpoint signaling pathway." (PMID 41009395, 2025). "Similar to induction of replication stress, Western blot analyses also showed a time-dependent, significant increase in levels of phosphorylated Chk1 and Chk2, demonstrating strong activation of both ATR-Chk1 and ATM-Chk2 DDR signaling pathways specifically in the cancer but not noncancerous cells." (PMID 34425836, 2021). "Further studies of various factors identified by our screens could facilitate successful stratification of cancer patients and/or elucidate new ATM-dependent pathways that compensate in the absence of functional ATR." (PMID 34329458, 2021). "Furthermore, since mutation of each of the five known Seckel genes, ATR, PCNT, CENPJ, CEP152 and RBBP8 (CtIP), cause genomic instability that is associated with apoptosis, it is possible that Seckel cells may not have the opportunity to accumulate cancer-causing mutations." (PMID 23166506, 2012). "It has been shown that ATM and ATR regulate partially overlapped but nonredundant downstream pathways during DNA repair, and defects in one PIKK protein might be compensated by the other to maintain the survival of cancer cells." (PMID 38041093, 2023). "ATR’s kinase does not play a major role for ATR–PINK1 interactions, which however, does not rule out the possibility that small molecules that disrupt the interface of both proteins could alter mitochondrial functionality and metabolism, thereby presenting a sound approach for cancer treatment." (PMID 40105243, 2025).